CNGA3 (cyclic nucleotide gated channel subunit alpha 3)
Description:
Pore-forming subunit of the cone cyclic nucleotide-gated channel. Mediates cone photoresponses at bright light converting transient changes in intracellular cGMP levels into electrical signals. In the dark, cGMP levels are high and keep the channel open enabling a steady inward current carried by Na(+) and Ca(2+) ions that leads to membrane depolarization and neurotransmitter release from synaptic terminals. Upon photon absorption cGMP levels decline leading to channel closure and membrane hyperpolarization that ultimately slows neurotransmitter release and signals the presence of light, the end point of the phototransduction cascade. Pore-forming subunit of the gustatory cyclic nucleotide-gated channel. In the taste buds, may sense oral extracellular pH and conduct ion currents that modulate the excitability of taste cells (By similarity). Conducts cGMP- and cAMP-gated ion currents, with permeability for monovalent and divalent cations (By similarity).
Synonyms: CNG3; CNCG3; CCNC1; CCNCa; ACHM2; CCNCalpha
Tractability: Small molecule: a structure with a bound ligand is known; it belongs to a druggable protein family. Antibody: UniProt places it where antibodies can reach, with high confidence; its Gene Ontology location is reachable by antibodies, with high confidence; UniProt predicts a signal peptide or a membrane-spanning region.
Gene: Protein-coding gene on chromosome 2 (98,346,188 to 98,399,797, forward strand). Ensembl gene ENSG00000144191.
Subcellular location: Cell membrane
Subcellular location (Human Protein Atlas): End piece; Mid piece; Principal piece
Gene Ontology:
Molecular function: cGMP binding; intracellularly cAMP-activated cation channel activity; intracellularly cGMP-activated cation channel activity; protein binding; ligand-gated monoatomic ion channel activity; cadherin binding; intracellularly cyclic nucleotide-activated monoatomic cation channel activity; monoatomic ion channel activity; myosin binding
Biological process: monoatomic cation transport; visual perception; monoatomic cation transmembrane transport; retina development in camera-type eye; signal transduction; inorganic cation import across plasma membrane; monoatomic ion transmembrane transport; monoatomic ion transport; response to cAMP; response to magnesium ion; transmembrane transport
Cellular component: intracellular cyclic nucleotide activated cation channel complex; plasma membrane; transmembrane transporter complex; cone photoreceptor disc membrane; photoreceptor outer segment membrane; axon initial segment; dendrite; glial cell projection; membrane; neuronal cell body; perikaryon
Genetic constraint (gnomAD): Loss-of-function variants: 44 observed, 50.26 expected, observed/expected ratio (o/e) 0.88, 90% interval 0.69 to 1.13. The upper end of that interval is the gene's LOEUF score, 1.13, which puts it in group 4 of 6, group 1 being the genes least tolerant of losing a copy. Missense variants: 893 observed, 935.6 expected, observed/expected ratio (o/e) 0.95, 90% interval 0.9 to 1.01. Synonymous variants: 394 observed, 390.39 expected, observed/expected ratio (o/e) 1.01, 90% interval 0.93 to 1.1.
Gene-disease validity (ClinGen):
ClinGen rates the evidence that CNGA3 causes each of these diseases.
CNGA3-related retinopathy (autosomal recessive): Definitive. A retinopathy, typically described as achromatopsia, caused by biallelic variants in the CNGA3 gene.
Homologues: Orthologues: macaque CNGA3 (96% identical), chimpanzee CNGA3 (92% identical), dog CNGA3 (85% identical), rabbit CNGA3 (84% identical), pig CNGA3 (83% identical), rat Cnga3 (79% identical), mouse Cnga3 (79% identical), guinea pig CNGA3 (76% identical), tropical clawed frog cnga3 (73% identical), zebrafish cnga3a (66% identical), zebrafish cnga3b (59% identical), Drosophila melanogaster CngA (47% identical), and 10 more. Paralogues in human: CNGA1 (61% identical), CNGA2 (60% identical), CNGA4 (43% identical), CNGB1 (28% identical), CNGB3 (26% identical), HCN4 (24% identical), HCN1 (23% identical), HCN2 (23% identical), KCNH3 (21% identical), HCN3 (21% identical), KCNH7 (21% identical), KCNH2 (20% identical), and 5 more.
Diseases named in the same sentence as CNGA3 in open-access papers:
CNGA3 is named in the same sentence as 42 diseases in open-access papers, as found by Europe PMC text mining. Sharing a sentence is not in itself a finding about the gene and the disease. The quoted sentences say what the papers report.
achromatopsia (78 papers, 2008 to 2026). Achromatopsia (ACHM) is a rare autosomal recessive retinal disorder characterized by color blindness, nystagmus, photophobia, and severely reduced visual acuity due to the absence or impairment of cone function. "We reported the phenotype in a patient with CNGA3-mediated achromatopsia, a novel patient variant (c." (PMID 40448196, 2025). "In contrast, CNGA3 variants are a prevalent cause of achromatopsia in Chinese and Korean patients, with the majority arising from missense changes." (PMID 40013354, 2025). "Since CNGA3-associated achromatopsia is inherited in autosomal recessive manner, one functioning allele should be sufficient to restore color vision." (PMID 40448196, 2025). "The CNGA3 gene is associated with Achromatopsia (MIM # 216900), which is characterized by color blindness, reduced visual acuity, and nystagmus." (PMID 40737315, 2025). "In this study, we present an achromatopsia patient with a novel homozygous variant in the CNGA3 gene." (PMID 40448196, 2025). "This missense mutation disrupts normal CNGA3 protein function associated with the phototransduction cascade and, as such, contributes to the development of achromatopsia in this family." (PMID 40737315, 2025). "Here, we present clinical features of a novel CNGA3 variant in an achromatopsia patient and demonstrate its pathogenicity by a three-dimensional (3D) proteoform-based structure-function analysis." (PMID 40448196, 2025). "As of January 2024, there were 199 CNGA3 variants with an association to achromatopsia in ClinVar with at least one peer-reviewed research article discussing the variant." (PMID 40448196, 2025). "Achromatopsia is an autosomal recessive genetic disease, and 95% of achromatopsia patients carry pathogenic mutations in the CNGA3 and CNGB3 genes." (PMID 40448196, 2025). "CNGA3 and CNGB3 functioned together by forming a heterotetramer cyclic nucleotide-gated (CNG) channel resulting in up to 95% of achromatopsia patients having pathogenic defects in the CNGA3/CNGB3 channel complex (cone CNG channel)." (PMID 40448196, 2025). "This frameshift mutation leads to the premature truncation of the CNGA3 protein, which is critical for cone photoreceptor function, resulting in the initial presentation of achromatopsia." (PMID 40737315, 2025). "Mutations in CNGA3 are thought to impair this process, resulting in achromatopsia, an unusual autosomal recessive condition that features deficient cone photoreceptor function, poor vision, nystagmus, and photosensitivity." (PMID 40737315, 2025). "To date, pathogenic variants in six genes have been associated with achromatopsia, five of which play vital roles in the cone phototransduction cascade (i.e., CNGA3, CNGB3, GNAT2, PDE6C, PDE6H, and ATF6)." (PMID 40448196, 2025). "This study report a novel missense variant in the cyclic nucleotide-gated channel 3 (CNGA3) gene identified by targeted gene panel sequencing approach in a Chinese family with achromatopsia." (PMID 39678380, 2024). "Currently, six genes that cause achromatopsia have been discovered, including CNGA3, CNGB3, GNAT2, PDE6C, PDE6H and ATF6." (PMID 38298913, 2024). "Each gene therapy contains either CNGB3 or CNGA3, based on the reasoning that mutations in these genes affect 80% of achromatopsia patients, and were packaged into an AAV capsid and then delivered by a subretinal injection after vitrectomy." (PMID 39273686, 2024). "Variants in the CNGA3 gene, located on chromosome 2q11, which encodes the alpha subunit of the cone photoreceptor cGMP-gated cation channel, are the cause of achromatopsia 2 (ACHM2; OMIM 216900)." (PMID 39678380, 2024). "In this study, a novel missense variant (c.524T>A p.Ile175Asn) of CNGA3 identified in a Chinese family with achromatopsia in conjunction with clinical data was first reported." (PMID 39678380, 2024).
achromatopsia (continued). "There are currently five gene therapy clinical trials registered for human patients at the phase I/II stage and for CNGA3 or CNGB3 causing achromatopsia." (PMID 39273686, 2024). "In this report, we outline the delineation of a VUS in CNGA3 in Case 2 as likely pathogenic which provides biallelic evidence of disease leading to the observed phenotypic features of achromatopsia." (PMID 37558662, 2023). "Achromatopsia is an autosomal recessive cone photoreceptor disease that is frequently caused by pathogenic variants in the CNGA3 gene." (PMID 36801918, 2023). "Here, we present a systematic functional analysis of 20 CNGA3 splice site variants detected in our large cohort of achromatopsia patients and/or listed in common variant databases." (PMID 36801918, 2023). "We identified variants believed to be disease causing in five of the known achromatopsia genes: CNGA3; CNGB3; GNAT2; PDE6C and PDE6H; and novel variants were identified in CNGB3 and PDE6C." (PMID 36980963, 2023). "Previously, the potency of gene therapy vectors for the treatment of CNGA3- or CNGB3-linked achromatopsia was assessed after subretinal or intravitreal injection of the gene therapy vector in gene-deficient animal models (i.e., mouse or dog)." (PMID 35562929, 2022). "Given our previous experience, we chose CNGA3-linked achromatopsia to develop a cell-based system to verify biological activity of AAV vectors designed to deliver a healthy CNGA3 gene copy into human cone photoreceptors." (PMID 35562929, 2022). "To date, there are about 197 different variants reported for CNGA3 responsible to cause different disease phenotypes, e.g., achromatopsia, cone–rod dystrophy, and retinitis pigmentosa (HGMD) amongst others." (PMID 35456423, 2022). "We investigated the structural basis and molecular/cellular effects of R410W, an achromatopsia-associated, presumed loss-of-function mutation in human CNGA3." (PMID 35233102, 2022). "Achromatopsia (OMIM:216,900), also called rod monochromatism, characterized by dysfunction of the cone photoreceptors was observed in 3 consanguineous families displaying mutations in CNGA3, CNGB3 and GNAT2, respectively." (PMID 35551639, 2022). "Intriguingly, a recent study reported outcome of a 3-year retinal gene therapy trial (AAV8.CNGA3) for nine patients affected with CNGA3-associated achromatopsia." (PMID 35456423, 2022). "Using a novel multimodal approach, we demonstrate for the first time that gene therapy can successfully activate dormant cone-mediated pathways in children with achromatopsia (CNGA3- and CNGB3-associated, 10–15 years)." (PMID 35998912, 2022). "To date, six genes (ATF6A, CNGA3, CNGB3, GNAT2, PDE6C, and PDE6H) are known to cause achromatopsia, with mutations in CNGA3 and CNGB3 responsible for more than 90% of cases." (PMID 35562929, 2022). "A canine model with two spontaneous mutations (R424W or V644del) mimicking the human CNGA3-associated achromatopsia has been shown a valuable system to study the cone-specific CNG channel function and for a proof-of-concept study of CNGA3 gene therapy." (PMID 32967234, 2020). "In contrast, our gene therapy approach for CNGA3-linked achromatopsia was designed to specifically treat cone photoreceptors." (PMID 32352493, 2020). "Achromatopsia linked to variations in the CNGA3 gene is associated with day blindness, poor visual acuity, photophobia, and involuntary eye movements owing to lack of cone photoreceptor function." (PMID 32352493, 2020). "Mutation in the cyclic nucleotide-gated channel alpha subunit (CNGA3) gene causes achromatopsia 3 with cone dysfunction." (PMID 32967221, 2020). "Mutations in the CNGA3 gene, which encodes the A subunit of the cyclic guanosine monophosphate (cGMP)-gated cation channel in cone photoreceptor outer segments, cause total colour blindness, also referred to as achromatopsia." (PMID 33374621, 2020).
achromatopsia (continued). "Nine patients (3 per dose group) with a clinical diagnosis of achromatopsia and confirmed biallelic disease-linked variants in CNGA3 were enrolled between November 5, 2015, and September 22, 2016." (PMID 32352493, 2020). "About 25% of human achromatopsia cases are caused by damaging mutations in the alpha subunit of the cone CNG channel (CNGA3)." (PMID 32260251, 2020). "Through exome sequencing in a consanguineous pedigree (PK004) with three affected children suffering from putative complete achromatopsia, we identified a homozygous nonsynonymous single-nucleotide variant (NM_001298.2:c.847C>T:p.Arg283Trp) in the CNGA3 gene." (PMID 31877759, 2019). "As the first identified and second most common cause of achromatopsia, Cnga3 mutations account for approximately 25% of all cases." (PMID 29131863, 2017). "Cpfl5 mice exhibit selective loss of cone ERG responses, similar to the electroretinographic phenotype of complete achromatopsia patients with Cnga3 mutations." (PMID 29131863, 2017). "Loss of CNGB3 has been associated with loss of its heterotetrameric partner CNGA3 since it regulates the expression of CNGB3 as was shown in the mouse model of CNGA3-achromatopsia before and after gene therapy." (PMID 28993665, 2017). "Recently, successful gene therapies have been reported in CNGA3-deficient sheep, a large-animal model of achromatopsia." (PMID 29131863, 2017). "The missense mutations for c.633T>A (p.D211E) and c.1006G>T (p.V336F) and the combined heterozygous mutations for c.997_998delGA and p.M424V in the CNGA3 gene is the cause for achromatopsia." (PMID 28350845, 2017). "In the majority of patients, achromatopsia is a channelopathy and caused by mutations in either the CNGA3 or CNGB3 gene, with CNGB3 being affected most commonly." (PMID 23601474, 2013). "Naturally occurring achromatopsia based on mutations in other genes have been described in Awassi sheep (CNGA3) and in mice (CNGA3, GNAT2 and PDE6C)." (PMID 23601474, 2013). "Achromatopsia results from mutations in one of three genes: cyclic nucleotide-gated channel, alpha-3 (CNGA3); cyclic nucleotide-gated channel, beta-3 (CNGB3); and guanine nucleotide-binding protein, alpha-transducing activity polypeptide 2 (GNAT2)." (PMID 18636117, 2008). "The frequency of CNGA3 mutations in UAE achromatopsia patients in this relatively small population (less than 1 million) remains to be determined." (PMID 18636117, 2008). "A more recent study in United Kingdom achromatopsia families showed that CNGA3 mutations accounted for up to 40% of the achromatopsia cases in the 22 families studied." (PMID 18636117, 2008). "In contrast, our study showed that the cases of achromatopsia in the two UAE families we examined were associated with CNGA3 mutations." (PMID 18636117, 2008). "The distinct proteotypic consequence of CNGA3 mutants shown in our analysis strongly supported the notion that gene supplementation may be the most widely applicable therapeutic option for CNGA3-associated achromatopsia patients." (PMID 40448196, 2025). "The presence of this variant in the affected individuals and its segregation within the family strongly supports its role in the observed phenotype, linking the CNGA3 variant to the clinical symptoms of achromatopsia, light sensitivity, poor eyesight, and nystagmus." (PMID 40737315, 2025). "There are 150 CNGA3 missense variants reported in achromatopsia patients, but the pathogenicity of 103 variants remains unknown due to inconclusive genetic information." (PMID 40448196, 2025). "Achromatopsia is caused by sequence variants in CNGA3, CNGB3, GNAT2, PDE6H, PDE6C, and ATF6." (PMID 39273686, 2024). "Biallelic mutations in CNGA3 are the second most common cause of achromatopsia (MIM #216900), a rare congenital autosomal recessive disorder that affects cone photoreceptor function and leads to poor visual acuity, photophobia, congenital nystagmus and complete color blindness." (PMID 36801918, 2023).